SPAG5 (sperm associated antigen 5)
Diseases named in the same sentence as SPAG5 in open-access papers (continued):
Sharing a sentence is not in itself a finding about the gene and the disease.
breast carcinoma (continued). "Therefore, SPAG5 contributed to the development of hormonal therapy resistance in ER+ breast cancer and the expression level was predictive on the survival outcomes of patients undergoing endocrine therapy." (PMID 31690268, 2019). "We considered that SPAG5 was correlated with mTOR signaling pathway activity during breast cancer treatment, and the cross-talk between the estrogen receptor and mTOR signaling pathway, the most well-known mechanism of endocrine resistance, led to poor prognosis of patients." (PMID 31690268, 2019). "The clinical impact of SPAG5 has been well documented in breast cancer." (PMID 30089483, 2018). "Interestingly, this effect was also highlighted upon depletion of the TEAD transcription factor, suggesting that SPAG5 could serve as a breast cancer target within the oncogenic transcriptional axis YAP/TAZ/TEAD." (PMID 33230261, 2021). "However, few studies focused on the prognostic value of SPAG5 in breast cancer patients." (PMID 31690268, 2019). "SPAG5 may also be used as a proliferation marker in early breast cancer." (PMID 30736840, 2019). "Thus, in addition to a potential prognostic biomarker, SPAG5 might act as a therapeutic target for breast cancer." (PMID 31690268, 2019). "The results showed that higher expression of SPAG5 was associated with worse RFS (n = 3557, HR = 1.72, 95% CI 1.54–1.94, p < 0.001), OS (n = 1117, HR = 1.86, 95% CI 1.46–2.37, p < 0.001), and DMFS (n = 1610, HR = 1.88, 95% CI 1.53–2.32, p < 0.001) in patients with breast cancer." (PMID 31690268, 2019). "Therefore, further researches on the role of SPAG5 in breast cancer are mandatory in the future." (PMID 31690268, 2019). "Similarly, we found that SPAG5 could predict prognosis of breast cancer patients with systemic treatment." (PMID 31690268, 2019). "Nevertheless, only two studies on estrogen receptor-positive breast cancer and non-small-cell lung cancer reported high SPAG5 expression by microarray analysis;14, 15 whether SPAG5 expression is related to the etiology and development of cervical cancer remains unclear." (PMID 24853425, 2014). "Of note, treatment of MDA-MB-231 breast cancer cells and MCF-10A cells stably overexpressing SPAG5 with Dasatinib and Verteporfin reduced SPAG5 protein level in a dose-dependent manner and affected their respective colony-forming ability." (PMID 33230261, 2021). "Conversely, loss of function of miR-10b-3p by using a specific miRNA inhibitor released SPAG5 transcript and protein expression in both MDA-MB-231 and MDA-MB-468 breast cancer cell lines and in MCF-10A cells." (PMID 33230261, 2021). "Collectively, these results indicate the strong interconnection within the network of three prognostic factors, SPAG5, YAP, and miR-10b-3p expression that also pairs with the prevalence of different cell populations in the identified breast cancer subtypes." (PMID 33230261, 2021). "Collectively, our data uncover an oncogenic feedback loop, comprising miR-10b-3p, SPAG5, and YAP/TAZ/TEAD, which fuels the aberrant proliferation of breast cancer." (PMID 33230261, 2021). "Meanwhile, we found that CEP55, HIST1H2BO, IFI6, KIAA0101, PBK, SPAG5, and SPP1 were significantly upregulated in breast cancer compared to normal samples." (PMID 34055036, 2021). "In cervical cancer, breast cancer, bladder cancer, HCC, lung cancer, prostate cancer and other malignancies, SPAG5 is highly expressed in tumor tissues, indicating a poor prognosis." (PMID 31985007, 2020). "Then, we examined MYCBP expression in 183 breast cancer patients using IHC and found that MYCBP protein expression is positively correlated with SPAG5 expression in breast cancer (R = 0.218, p < 0.001), as well as in TNBC (R = 0.321, p < 0.001)." (PMID 30736840, 2019). "b Regression analysis identified a positive relationship between SPAG5 and MYCBP protein expression levels in breast cancer tissues." (PMID 30736840, 2019).
breast carcinoma (continued). "Analysis of SPAG5 in 1,379 FBCs in GOBO (Gene expression-based Outcome for Breast cancer Online) confirmed that it was prognostic for distant disease free survival in ER positive, but not ER negative FBC (data not shown)." (PMID 24194916, 2013). "Previous artificial neural network-based data mining research suggested that the transcript and protein products of SPAG5 were independent predictors for response to combination chemotherapy in oestrogen receptor (ER)-negative (ER-) breast cancer." (PMID 38610947, 2024). "Interestingly, SPAG5’s expression is higher (ANOVA test P = 1.3655e−94 and ANOVA test P = 1.3655e−94) in the Luminal B, HER2, and basal-like breast cancer subtypes, as compared to the Luminal A subtype." (PMID 33230261, 2021). "Correspondingly, SPAG5 is strongly expressed (t test P value = 4.4658e−12 and t test P value = 3.2145 e−43) in breast cancer specimens compared to nontumoural tissues, in both METABRIC and in the TCGA dataset." (PMID 33230261, 2021). "Accordingly, we tested whether treatment with Agave can affect SPAG5 expression in MDA-MB-231 and in MDA-MB-468 breast cancer cell lines." (PMID 33230261, 2021). "Importantly, high expression of SPAG5 is linked to the transcriptional signature of activated YAP/TAZ in breast cancer patients, implying the involvement of YAP/TAZ in the oncogenic activity of SPAG5." (PMID 33230261, 2021). "Our results failed to yield any correlation between SPAG5 and NuMA mRNA levels which implies independence of these genes in breast cancer pathogenesis." (PMID 32838814, 2020). "Furthermore, a significant positive correlation between SPAG5 and MYCBP protein expression was also observed in breast cancer and TNBC tissues in our cohort." (PMID 30736840, 2019). "In our study, using a large combined cohort, we demonstrated that SPAG5 expression was significantly higher in patients with hormone negative (ER- and PR-) breast cancer." (PMID 31690268, 2019). "a SPAG5 mRNA levels in TCGA breast cancer mRNA dataset of tumor(n = 737) versus non-tumor tissues(n = 120)." (PMID 30736840, 2019). "In our study, we found that SPAG5 expression was not predictive in high grade (poorly differentiated) breast cancer patients, perhaps because poorly differentiated breast cancer cells proliferated fast and had a poor response to all kinds of therapies including hormonal therapy." (PMID 31690268, 2019). "Moreover, SPAG5 was an important determinant of survival in HER2 negative rather than HER2 positive breast cancer patients." (PMID 31690268, 2019). "A recent study reported that the transcript and protein products of SPAG5 might be independent prognostic and predictive biomarkers for chemotherapy sensitivity, particularly in ER negative (ER-) breast cancer." (PMID 31690268, 2019). "SPAG5 upregulation in tumor tissues indicated poor disease-free survival (DFS, HR = 2.470, 95%CI 1.203–5.073, p = 0.016) and overall survival (OS, HR = 3.327, 95%CI 1.204–9.196, p = 0.029) and it was also an independent prognostic factor for breast cancer patients." (PMID 30736840, 2019). "In addition, SPAG5 could only serve as a survival predictor in ER+, but not ER- breast cancer patients." (PMID 31690268, 2019).
cervical cancer (15 papers, 2014 to 2024). A primary or metastatic malignant neoplasm involving the cervix. "Sperm-associated antigen 5 (SPAG5) has been recently identified as a prognostic biomarker for breast and cervical cancers." (PMID 35704638, 2022). "Sperm-associated antigen 5 (SPAG5) is a mitotic spindle-associated protein that is involved in various biological processes in cervical cancer and bladder urothelial carcinoma." (PMID 30736840, 2019). "Previously, we found that sperm-associated antigen 5 (SPAG5) was upregulated in pelvic lymph node metastasis–positive cervical cancer." (PMID 24853425, 2014). "Upregulation of SPAG5 was associated with poor prognosis in cervical cancer." (PMID 34796102, 2021). "SPAG5 is upregulated in cervical cancer and bladder cancer and implicated in tumorigenesis." (PMID 30736840, 2019). "Upregulation of SPAG5 in cervical cancer was reported to associate with poor prognosis." (PMID 30089483, 2018). "Consistently, during SPAG5 taxol treatment for cervical cancer, SPAG5 was observed to regulate mTOR activity." (PMID 34162370, 2021). "In cervical cancer cell lines, SPAG5 down-regulation resulted in inhibition of cell growth and proliferation by inducing G2/M phase cell cycle arrest." (PMID 31690268, 2019). "Overexpression of SPAG5 was reported in cervical cancer, pancreatic cancer and non-small-cell lung cancer." (PMID 30089483, 2018). "Previous studies showed that SPAG5 overexpression can predict poor prognosis in lung cancer and cervical cancer and alter sensitivity to taxol treatment via the mTOR signaling pathway in cervical cancer." (PMID 27037000, 2016). "SPAG5 was recently identified as an oncogene participating in lung cancer and cervical cancer progression." (PMID 27037000, 2016). "Combining the function of SPAG5 in cell spindle construction and mitosis with our findings, we believe that SPAG5 contributes to cervical cancer progression." (PMID 24853425, 2014). "To determine how SPAG5 regulates the biological behavior of cervical cancer cells, we designed four siRNAs targeting SPAG5 mRNA to eliminate SPAG5 regulation in cervical cancer cells and to study its function." (PMID 24853425, 2014). "Considering the vital role of SPAG5 in cell mitosis, we focused on SPAG5 protein in this study to search for its functions in cervical cancer." (PMID 24853425, 2014). "In general, SPAG5 upregulation relates to poor prognosis in cervical cancer patients, and SPAG5 is a regulator of mTOR activity during taxol treatment in cervical cancer." (PMID 24853425, 2014). "Under SPAG5 downregulation, the sensitivity of cervical cancer cells differed according to taxol dose, which correlated with mammalian target of rapamycin (mTOR) signaling pathway activity." (PMID 24853425, 2014). "The aim of this study is to examine the role of SPAG5 in the proliferation and tumorigenicity of cervical cancer and its clinical significance in tumor progression." (PMID 24853425, 2014). "SPAG5 was not only an independent prognostic factor for cervical cancer patients, but also had an important role in the effects of chemotherapy." (PMID 24853425, 2014). "To explore the clinical significance of SPAG5 expression in cervical cancer patients, we analyzed the relationship between SPAG5 expression and the patients' clinical data." (PMID 24853425, 2014). "We treated SPAG5 knockdown and NC cervical cancer cells with different doses of taxol and identified the different roles of SPAG5 under these doses." (PMID 24853425, 2014). "Also, SPAG5 was reported to overexpress in cervical cancer, prostate cancer, gastric cancer and lung cancer, and contributed to carcinogenesis." (PMID 35138218, 2022). "SPAG5 upregulation was related to poor prognosis in cervical cancer patients." (PMID 30736840, 2019).
cervical cancer (continued). "Previous studies indicated that the overexpression of SPAG5 gene might act as a potential biomarker which predicted poor prognosis in patients with lung cancer and cervical cancer." (PMID 31690268, 2019). "High SPAG5 expression was an independent prognostic factor for cervical cancer patients." (PMID 24853425, 2014). "mTOR signaling pathway inhibitors might be a new therapeutic treatment in cervical cancer, and SPAG5 expression in cervical cancer may be a potential indicator for mTOR inhibitor treatment." (PMID 24853425, 2014). "SPAG5 downregulation in cervical cancer cell lines inhibited cell viability and growth." (PMID 24853425, 2014). "Searching further for the related mechanisms, a recent study indicated that SPAG5 regulated the sensitivity to taxol (aka., paclitaxel), a standard chemotherapy for TNBC, in cervical cancer cells (HeLa and SiHa) through altering mTOR activity." (PMID 38610947, 2024). "SPAG5 knockdown sensitized TNBC and cervical cancer cell lines to Olaparib and Taxol." (PMID 39164278, 2024). "SPAG5 was upregulated in tumor tissue compared with paired adjacent noncancerous tissues; SPAG5 upregulation in tumor tissues indicated poor disease-free survival, which was also an independent prognostic indicator for cervical cancer patients." (PMID 24853425, 2014). "The IHC staining also demonstrated clearly higher SPAG5 protein levels in cervical cancer tissues than in adjacent noncancerous tissues (ANT; P<0.0001)." (PMID 24853425, 2014).
hepatocellular carcinoma (15 papers, 2018 to 2024). A malignant tumor that arises from hepatocytes. "High expression of SPAG5 is closely associated with the progression of various cancers, such as breast cancer and hepatocellular carcinoma." (PMID 38807081, 2024). "SPAG5 promoted the progression of hepatocellular carcinoma through CEP55-mediated activation of the PI3K/AKT pathway." (PMID 35138218, 2022). "SPAG5 acts as a prognostic indicator in hepatocellular carcinoma and as an oncogene, mediated by the PI3K/AKT pathway." (PMID 34162370, 2021). "Increased SPAG5 expression was reported to be accompanied by reduced survival in hepatocellular carcinoma." (PMID 30736840, 2019). "This study investigated the function and clinical significance of SPAG5 protein expression in hepatocellular carcinoma." (PMID 30249289, 2018). "Sperm-associated antigen 5 (SPAG5) is essential for the spindle apparatus organization and chromosome segregation, but its role in hepatocellular carcinoma (HCC) remains undefined." (PMID 30089483, 2018). "To identify the potential roles of SPAG5 in the development and progression of hepatocellular carcinoma, we first examined SPAG5 expression in 136 hepatocellular carcinoma (HCC) tissue samples and corresponding adjacent tissues by qRT-PCR." (PMID 30249289, 2018). "In other cancer types, the SPAG5 expression and function were also correlated with miRNAs, such as miR-1179 in non-small cell lung cancer, miR-539 in prostate cancer and miR-363-3p in hepatocellular cancer." (PMID 38610947, 2024). "SPAG5 promotes hepatocellular cancer proliferation and acts as an oncogene." (PMID 35853859, 2022). "Indeed, downregulation of miR-363-3p allows SPAG5 to exert its oncogenic activity initiating PI3K/AKT pathway via CEP55 interaction in hepatocellular carcinoma." (PMID 33230261, 2021). "Previous studies have reported that SPAG5 triggers PI3K/AKT signaling pathway to exert oncogenic activities in various cancers, such as hepatocellular carcinoma, and gastric cancer." (PMID 38807081, 2024). "It has been reported that the interaction between CEP55 and SPAG5 triggered the phosphorylation of AKT at Ser473 and activated the PI3K/AKT pathway to exhibit pro-hepatocellular carcinoma activities." (PMID 37274251, 2023). "SPAG5 is a mitotic spindle protein, which promotes cancer cell proliferation and invasion by activating AKT/mTOR pathway in bladder and hepatocellular cancer." (PMID 36304306, 2022). "The Expression DIY module in the GEPIA database was used to analyze SPAG5 expression profile in the HCC (liver hepatocellular carcinoma, LIHC) and the normal tissues, which showed an increased trend of circFOXM1 transcripts in HCC tissues than in normal control tissues." (PMID 34903799, 2021). "SPAG5, which interacts with centrosomal protein CEP55 resulting in the phosphorylation of AKT at Ser473, promotes hepatocellular carcinoma growth via CEP55-mediated Phosphatidyl inositol -3- hydroxykinase (PI3K)/(protein kinase B) AKT pathway." (PMID 34796102, 2021). "However, the role of SPAG5 in hepatocellular carcinoma (HCC) remains unknown." (PMID 30249289, 2018).
lung carcinoma (11 papers, 2016 to 2024). "SPAG5 is an emerging oncogene in lung cancer, and associated with unfavorable prognosis in patients with lung adenocarcinoma." (PMID 35996496, 2022). "Previously, both SPAG5 and TOP2A were identified as hub genes associated with accelerated COVID-19 infection in lung cancer patients." (PMID 39596028, 2024). "SPAG5 played crucial roles in cancer progression and was found to be upregulated in cervical, pancreatic, and lung cancers." (PMID 34055036, 2021). "For instance, RAD51 and SPAG5 were identified to be associated with poor survival in patients with early stage LUAD but their function in lung cancer has not been extensively characterized." (PMID 36304306, 2022). "qRT-PCR confirmed that the expression level of CDKN3, MKI67, CEP55, SPAG5, AURKA, TOP2A were highly expressed in lung cancer tissues." (PMID 35178291, 2022). "We found that E2F1 regulated genes enriched in ‘cell division’ across all three subtypes, with three target genes in the GO term commonly regulated in lung cancers: CCNF (cyclin F), NCAPH (Non-SMC Condensin I Complex Subunit H), SPAG5 (Sperm Associated Antigen 5)." (PMID 29866045, 2018).
prostate carcinoma (10 papers, 2016 to 2024). A carcinoma that arises from epithelial cells of the prostate gland. "SPAG5 expression in prostate cancer was associated with cancer progression and unfavorable outcomes." (PMID 30736840, 2019). "SPAG5 expression was gradually increased during prostate cancer progression and its level was significantly associated with lymph node metastasis, clinical stage, Gleason score, and biochemical recurrence; moreover, miR-539 can inhibit prostate cancer progression by directly targeting SPAG5." (PMID 31985007, 2020). "Knockdown of SPAG5 could significantly suppress proliferation and invasion of prostate cancer cells in vitro, along with inhibiting the growth and metastasis of tumor in vivo." (PMID 31690268, 2019). "SPAG5 was previously demonstrated to be targeted by miR-539 in prostate cancer." (PMID 30089483, 2018). "MiR-539 inhibits prostate cancer progression by directly targeting SPAG5." (PMID 28328537, 2017).